FOXM1 (forkhead box M1)
Diseases named in the same sentence as FOXM1 in open-access papers (continued):
Sharing a sentence is not in itself a finding about the gene and the disease.
ovarian carcinoma (continued). "Olaparib activated the FOXM1 pathway as an adaptive cellular response to DNA damage, and FOXM1 inhibition enhanced sensitivity to PARPi in ES-2 and OVCA420 ovarian cancer cells." (PMID 38356722, 2024). "This study reveals a novel regulatory mechanism of ALKBH5 in ovarian cancer: it modifies PVT1 RNA and subsequently stabilizes FOXM1." (PMID 38098223, 2024). "Given the well-documented role of FOXM1 in cell cycle progression and cellular proliferation, in particular, of ovarian cancer cells, we next asked whether domatinostat, as an inhibitor of FOXM1 expression, exhibits growth inhibitory effects on ovarian cancer cells." (PMID 37445993, 2023). "Cell viability, as well as protein and mRNA expression of FOXM1 and its transcriptional target survivin, was examined after domatinostat treatment of TOV21G and SKOV3 ovarian cancer cell lines in the absence or presence of cisplatin and paclitaxel." (PMID 37445993, 2023). "FOXM1 recognizes two conserved binding sites that flank the TSS of DLX1, thus upregulating its expression in high-grade ovarian cancer." (PMID 37835497, 2023). "FOXM1 knockdown also reduced the mRNA levels of survivin/BIRC5, suggesting that the BIRC5 gene was a transcriptional target of FOXM1 in ovarian cancer cells just as in other cell types reported previously." (PMID 37445993, 2023). "Based on the relationship between virtual docking energy, affinity, and anti-ovarian cancer activity of compounds, a more reliable binding conformation of FDI-6 and FOXM1 was identified." (PMID 36505747, 2022). "We next measured known FOXM1 downstream targets CCNB1 and CDC25B expression by qPCR in ovarian cancer cells treated with compounds (40 μm; 48 h)." (PMID 35680842, 2022). "The SOCS7 correlates with HGSOC and suppresses its tumorigenesis through regulating HuR and FOXM1, which also suggests that SOCS7 is a prospective biomarker for the clinical management of ovarian cancer, especially HGSOC." (PMID 35624501, 2022). "DZY-4 showed the highest affinity to FOXM1 and its IC50 values for both ovarian cancer cells were comparable to those of cisplatin." (PMID 36505747, 2022). "In ovarian cancer, MFAP2 promotes β-catenin transfer from the cytoplasm to the nucleus via the FoxM1/β-Catenin signal pathway, increasing the glycolysis-related gene (GLUT1 and HK2) expression levels in A2780 and SKOV3 cells." (PMID 36530974, 2022). "However, the tumor tissue culture model of ovarian carcinoma appears to be suitable for stratification of patients that might benefit from clinically applicable therapeutics plus thiostrepton and pathways involved in the FOXM1 regulation might be comprehended." (PMID 33668819, 2021). "Finally, regarding the timing of these events in ovarian cancer, it is known that FOXM1 is expressed in HGSC precursor lesions in the FTE, which may, along with other proteins such as cyclin E1, increase RS, thus providing a selective advantage for RHNO1 co-expression." (PMID 33890574, 2021). "Lung cancer (H1703, A549) and ovarian cancer (PEO1, OVCAR3) cells treated with sublethal concentrations of carboplatin display a prominent increase in FOXM1 protein levels." (PMID 34262016, 2021). "Third, T-type Ca2+ channels, which are aberrantly overexpressed in ovarian cancer, can activate the PI3K/AKT pathway, thus antagonizing FOXO3A nuclear retention and promoting FOXM1 expression." (PMID 34205406, 2021). "Growth factor receptor-bound protein 7 (GRB7), which is a signal transducing adaptor protein that is overexpressed in ovarian cancer, promotes constitutive activation of the MAPK/ERK pathway and thereby leads to enhanced FOXM1 activity." (PMID 34205406, 2021). "In ovarian cancer, OTUB1 promoted ovarian cancer cell proliferation, invasion, and tumor growth through deubiquitination and stabilization of FOXM1." (PMID 34205406, 2021).
ovarian carcinoma (continued). "DDX23 silencing reduced the production of FOXM1C, the major oncogenic transcript of FOXM1 in ovarian cancer, thereby decreasing the FOXM1 protein expression and attenuating the malignant progression of ovarian cancer." (PMID 34966670, 2021). "For example, treatment of ovarian cancer patient tissues ex vivo with the PARPi olaparib increased BRCA1, BRCA2, RAD51, and FOXM1 gene expression, and treatment of the tissues with olaparib and thiostrepton reversed this effect." (PMID 34205406, 2021). "Elevated FoxM1 expression is triggered by the constitutive activation of ERK, which leads to enhanced cell motility in ovarian cancer." (PMID 32429421, 2020). "To confirm this, we established cisplatin resistant ovarian cancer cell line using TOV-21G cells, which have low FOXM1 expression than SKOV-3 cell and performed an immunoblotting assay in TOV-21G and cisplatin-resistant TOV-21G cells." (PMID 33053721, 2020). "Previously, we found that FOXM1 regulates the transcriptional activation of GLUT1 in HCC and ovarian cancer." (PMID 32174012, 2020). "In another study, co-regulation and functional co-operativity of a H2H pair, FOXM1 and RHNO1, was also proved in ovarian cancer." (PMID 33488665, 2020). "Univariate and multivariate analyses of the correlation of CDCA5, FOXM1, KIF15, MCM2, and ZWINT expression with overall survival (OS) among epithelial ovarian cancer patients." (PMID 31708970, 2019). "For example, high expression of forkhead box protein M1 (FOXM1) was shown to contribute to paclitaxel resistance and correlated with survival of ovarian carcinoma." (PMID 29494610, 2018). "In agreement, overexpression of the tumour suppressor microRNA miR-506 can induce senescence in ovarian cancer cells through repressing CDK4 and −6 expression and its activation of FOXM1." (PMID 29180117, 2018). "The TCGA group has identified several pathways that are commonly altered in ovarian cancer, including the RB1 signalling pathway, PI3K/RAS signalling pathway, FOXM1 transcription factor network and HR pathways." (PMID 29116111, 2017). "Based on the relationship between OTUB1 and FOXM1, and FOXM1's enhancement of ovarian cancer chemoresistance, the effect of OTUB1 and the OTUB1-FOXM1 axis on ovarian cancer chemoresistance is a curious question for future studies." (PMID 27167337, 2016). "The FOXM1 transcription factor network is frequently activated in high-grade serous ovarian cancer (HGSOC), the most common and lethal subtype of epithelial ovarian cancer (EOC)." (PMID 26243836, 2015). "In the present study, we show that FOXM1 is a critical regulator of the epithelial-mesenchymal transition (EMT), stemness, and chemoresistance in ovarian cancer cells." (PMID 25537512, 2015). "We previously demonstrated the molecular role of FOXM1 in mediating the biological effects of GEN and DFOG in human ovarian cancer cell lines, including the SKOV3 cell line." (PMID 24959264, 2014). "Attenuating FOXM1 and EXO1 expression by small interfering RNA, augments the chemotherapy efficacy against ovarian cancer." (PMID 24824601, 2014). "Our results suggest that casticin induces apoptosis in ovarian cancer cells (SKOV3 and A2780) through the regulation of FOXO3a/FoxM1 signaling." (PMID 23761826, 2013). "To probe the oncogenic roles of FOXM1 in ovarian cancer, we assessed the functional effects of two active FOXM1 isoforms, FOXM1B and FOXM1C, on A2780cp and OVCA433 cells." (PMID 21858223, 2011). "Since ERK lies up-stream of FOXM1, we reasoned that inhibition of ERK activity should abrogate cell migration of ovarian cancer cells through down-regulating FOXM1." (PMID 21858223, 2011). "Furthermore, inhibiting FoxM1 or overexpressing miR-370 can reverse the promoting effect of lncRNA-PVT1 on the malignant progression and chemoresistance of ovarian cancer." (PMID 40486884, 2025).
ovarian carcinoma (continued). "The results of various studies have suggested that the expressions of stem cell markers, such as NANOG, SOX2, forkhead-box protein M1 (FOXM1), and OCT4, in ovarian cancer mirror their tumorigenic potential, as well as resistance to paclitaxel, cisplatin, methotrexate, and adriamycin cells." (PMID 38201468, 2023). "As such, FOXM1 is a highly attractive therapeutic target in the treatment of ovarian cancer, but there has been no clinically tested FOXM1 inhibitor to date." (PMID 37445993, 2023). "The interaction between Cyclin B1 and FOXM1 was particularly pronounced in UCEC and ovarian cancer." (PMID 35672443, 2022). "As a FOXM1 target gene, KIF20A increases the proliferation and invasion of ovarian cancer cells." (PMID 35410446, 2022). "XST-20 (25 and 50 μM) significantly reduced the protein level of CCNB1 and PLK1 while FOXM1 protein level was not changed in three ovarian cancer cell lines." (PMID 35680842, 2022). "FOXM1 enhances aggressiveness via transcriptional upregulation of DLX1 and EXO1 in ovarian cancer." (PMID 35680842, 2022). "Although in vitro ovarian cancer models provide invaluable insight into the function of FOXM1 in ovarian cancer, cell lines do not adequately recapitulate in vivo disease." (PMID 34205406, 2021). "The overabundance of T-type Ca2+ channels in ovarian cancer leads to PI3K/AKT overexpression and, consequently, treatment with mibefradil, which is a calcium channel blocking agent, decreased nuclear FOXM1 protein levels and its binding to the BIRC5 (survivin) promoter in EOC cells." (PMID 34205406, 2021). "FOXM1, as a transcription factor, regulated many important proliferation-related target genes (AURB, CCNB1, BIRC5, CDC25, and PLK1, etc.)and was important oncogenic driver in ovarian cancer progression." (PMID 34966670, 2021). "To address whether FOXM1 and RHNO1 expression correlates in biological contexts unrelated to ovarian cancer or its progenitor cells, we analyzed in silico gene expression data sets, including normal and cancer tissues and cells, and mouse and human data." (PMID 33890574, 2021). "To date, transgenic mouse models have not been utilized to interrogate the oncogenic function of FOXM1 in ovarian cancer." (PMID 34205406, 2021). "While not yet explored in ovarian cancer, investigations in other cancers have shed light on the role of FOXM1 in TME development and maintenance." (PMID 34205406, 2021). "Additional proteins, which are not classical oncogenes, are also known to upregulate FOXM1 expression in ovarian cancer." (PMID 34205406, 2021). "Although not addressed in ovarian cancer, there is evidence that stress response proteins increase FOXM1 expression; this suggests that FOXM1 promotes cell survival in harsh conditions." (PMID 34205406, 2021). "There is also evidence that FOXM1 targets E-cadherin, although this has not been reported in ovarian cancer." (PMID 34205406, 2021). "To identify the effects of RAME in ovarian cancer, RNA sequencing was performed in RAME-treated ovarian cancer cells; we found that RAME treatment downregulated the genes closely involved with the target genes of the transcription factor Forkhead box M1 (FOXM1)." (PMID 33053721, 2020). "Since RAME inhibits the expression of FOXM1 and its target genes, we hypothesized that RAME would also decrease the migration and invasion abilities of ovarian cancer cells." (PMID 33053721, 2020). "In addition, we detected elevated FOXM1 and ABCC5 mRNA levels in paclitaxel-resistant ovarian cancer SKOV3R cells compared with parental SKOV3 cells." (PMID 28277541, 2017). "Besides NID1, several regulators, such as HPIP, NANOG and FOXM1, have been reported to promote EMT of ovarian cancer cells and then confer them drug resistance, involving PI3K/AKT pathway, STAT3 pathway, etc." (PMID 28416770, 2017).
ovarian carcinoma (continued). "In addition, SFRP5 expression inversely correlated with FOXM1 expression in ES-2 and TOV-21G ovarian cancer cells." (PMID 25537512, 2015). "Our findings indicate that targeting FOXM1 and its target gene EXO1 could improve cisplatin effect in ovarian cancer, confirming their role in modulating cisplatin sensitivity." (PMID 24824601, 2014). "Although EXO1 knock-down did not affect the expression of FOXM1, it did partly recapitulate the cisplatin sensitization effect of FOXM1 silencing in ovarian cancer cells." (PMID 24824601, 2014). "Taken together, our results suggest that elevated FOXM1 may be a prognostic marker of EOC and that FOXM1 may serve as a promising therapeutic target for inhibition of ovarian cancer progression." (PMID 24885308, 2014). "Our data showed that casticin elicited a marked effect on apoptosis in ovarian cancer cells, as demonstrated by histone/DNA ELISA results which showed the activation of caspase-3 and cleavage of PARP, accompanied by the downregulation of FoxM1 expression." (PMID 23761826, 2013). "Here, our data show that GRB7 regulates ERK activity and the FOXM1 expression orderly and is in agreement with our previous reports, indicating that the overexpressed GRB7 enhances ovarian cancer cell growth and cell migration/invasion through elevating ERK and FOXM1 activities." (PMID 23285101, 2012). "Though it gave us a clue that the transactivation of FOXM1 depends on phosphorylation by ERK at the post-transcriptional level, there is lack of reports regarding the functional attributes of activated ERK/FOXM1 signaling axis in ovarian cancer." (PMID 21858223, 2011). "We speculated that elevated FOXM1 expression is triggered by the constitutive activation of ERK, which leads to enhanced cell motility in ovarian cancer." (PMID 21858223, 2011). "Although FOXM1 was originally identified as being frequently deregulated in serous ovarian carcinomas, the predominant histotype, a subsequent study demonstrated that FOXM1 was similarly overexpressed in non-serous (clear cell and endometrioid) ovarian carcinomas as well as in serous ones." (PMID 37445993, 2023). "Finally, in ovarian cancer, DLX1 is a direct target of Forkhead Box M1 (FOXM1) TF." (PMID 37835497, 2023). "In ovarian cancer, FOXM1 also induces the expression of integrins and matrix proteins: ITGB1, ITGAV, ITGA5, LMNB1, and FN1, which may facilitate adhesion of ovarian cancer cells to new organs." (PMID 34205406, 2021). "To deeply investigate the phenomenon of ovarian cancer cell viability and apoptosis induced by circular PVT1, we conducted bioinformatics analysis and found circular PVT1 regulated miR-149-5p in the form of ceRNA, and miR-149-5p directly bond to 3'UTR of FOXM1 mRNA to repress FOXM1 expression." (PMID 33391456, 2021). "Nevertheless, no studies towards FOXM1-induced effects and mechanism in ovarian cancer were shown." (PMID 33391456, 2021). "However, the intracellular mechanisms by which casticin induces apoptosis in ovarian cancer cells via the regulation of FOXO3a/FoxM1 signaling have never been examined." (PMID 23761826, 2013). "Indeed, our in vitro and in vivo tumorigenic studies clearly show that the ovarian cancer cell growth and cell migration/invasion are remarkably reduced upon treatments of PD98059 or U01260, and Thiostrepton via targeting MEK/ERK and FOXM1 activities respectively." (PMID 23285101, 2012). "We also describe the regulatory mechanism of FoxM1/β-catenin and the inhibition of these signaling using the FoxM1 inhibitor, thiostrepton and β-catenin inhibitor, FH535 could synergistically abrogate the ovarian cancer growth, migration/invasion as well as in vitro and in vivo tumor growth." (PMID 29423068, 2018). "Thus far, the role of FOXM1 in cisplatin resistance of ovarian cancer has not been elucidated." (PMID 24824601, 2014).
ovarian carcinoma (continued). "However, the sensitization effect of STL001 was absent in ovarian cancer and TNBC cells with stable shRNA-mediated FOXM1-knockdown." (PMID 38697979, 2024). "Interestingly, paclitaxel treatment resulted in down-regulation of FOXM1 in SKOV-3 but not in the resistant cell line SKOV3-TR, implying a role of FOXM1 in mediating paclitaxel resistance in ovarian cancer cells." (PMID 25411964, 2014). "Although the effect of LSD1 inhibition on FOXM1 expression was not investigated in the study, these findings together suggest the possibility that LSD1 plays an essential role in the growth and survival of ovarian cancer cells through the activation of the FOXM1–survivin axis." (PMID 37445993, 2023).